KLK4 (kallikrein related peptidase 4)
Description:
Has a major role in enamel formation. Required during the maturation stage of tooth development for clearance of enamel proteins and normal structural patterning of the crystalline matrix (By similarity).
Synonyms: KLK-L1; EMSP1; PRSS17; PSTS; EMSP; AI2A1; ARM1; kallikrein
Tractability: Small molecule: a structure with a bound ligand is known; a high-quality ligand is known; it has a high-quality binding pocket. Antibody: its Gene Ontology location is reachable by antibodies, with high confidence; UniProt places it where antibodies can reach, with medium confidence; UniProt predicts a signal peptide or a membrane-spanning region. PROTAC: a small molecule that binds it is known.
Target class: Serine protease; Enzyme; Serine protease PA clan; Serine protease S1A subfamily; Protease
Gene: Protein-coding gene on chromosome 19 (50,906,351 to 50,911,395, reverse strand). Ensembl gene ENSG00000167749.
Subcellular location: Secreted
Gene Ontology:
Molecular function: protein binding; serine-type endopeptidase activity; serine-type peptidase activity
Biological process: amelogenesis; extracellular matrix disassembly; protein maturation; proteolysis
Cellular component: extracellular region; secretory granule
Genetic constraint (gnomAD): Loss-of-function variants: 28 observed, 26.16 expected, observed/expected ratio (o/e) 1.07, 90% interval 0.79 to 1.47. The upper end of that interval is the gene's LOEUF score, 1.47, which puts it in group 6 of 6, group 1 being the genes least tolerant of losing a copy. Missense variants: 344 observed, 340.27 expected, observed/expected ratio (o/e) 1.01, 90% interval 0.93 to 1.11. Synonymous variants: 142 observed, 147.25 expected, observed/expected ratio (o/e) 0.96, 90% interval 0.84 to 1.11.
Homologues: Orthologues: chimpanzee KLK4 (99% identical), macaque KLK4 (89% identical), pig KLK4 (78% identical), rabbit KLK4 (70% identical), rat Klk4 (70% identical), guinea pig KLK4 (70% identical), mouse Klk4 (69% identical), dog KLK4 (63% identical), tropical clawed frog klk1 (35% identical), Drosophila melanogaster CG32808 (27% identical), Drosophila melanogaster CG17404 (25% identical), Drosophila melanogaster CG4477 (24% identical), and 8 more. Paralogues in human: KLK5 (50% identical), KLK7 (44% identical), KLK14 (41% identical), KLK8 (39% identical), KLK12 (39% identical), KLK11 (38% identical), KLK2 (38% identical), KLK3 (37% identical), KLK1 (36% identical), PRSS58 (27% identical), TMPRSS4 (27% identical), PRSS54 (19% identical).
Diseases named in the same sentence as KLK4 in open-access papers:
KLK4 is named in the same sentence as 58 diseases in open-access papers, as found by Europe PMC text mining. Sharing a sentence is not in itself a finding about the gene and the disease. The quoted sentences say what the papers report.
ovarian cancer (32 papers, 2002 to 2024). A primary or metastatic malignant neoplasm involving the ovary. "Elevated KLK4 expression has been shown to be associated with poor prognosis in breast cancer and ovarian cancer." (PMID 39061962, 2024). "According to Obiezu 19, 21, overexpression of KLK4 induces proliferation and increases the risk of recurrence and death in patients with ovarian cancer." (PMID 34476001, 2021). "In case of ovarian cancer, a significant association was observed between elevated KLK4 mRNA and protein expression and poor clinical outcome, including progression-free and overall survival." (PMID 30811511, 2019). "In this ovarian cancer cohort, however, also a significant association of elevated KLK4 mRNA levels with PFS was observed (p = 0.032)." (PMID 30811511, 2019). "In a secretome and degradome profiling study, co-overexpression of KLK4–7 resulted in distinct more than two-fold changes in relative protein abundances as compared to KLK4–7-deficient ovarian cancer cells." (PMID 31307411, 2019). "KLK4 expression is known to correlate with prostate and ovarian cancer, and AR signaling in association with TGF-β signaling is well-studied in these tissues/cells." (PMID 29249975, 2017). "Elevated KLK4 levels were frequently associated with higher tumor grade in endometrial and prostate cancer and poor prognosis in ovarian cancer." (PMID 25888189, 2015). "KLK5 and KLK4 have been associated with poor prognosis in ovarian cancer, and KLK5 has also been shown to be associated with poor prognosis in breast cancer." (PMID 24510347, 2014). "An early study showed that expression of KLK4 in ovarian cancer tissues is associated with resistance to a first line, clinically-used chemo-agent paclitaxel in EOC patients." (PMID 24043563, 2014). "We wished to determine the mechanism of action underlying the poor prognosis and chemoresistance previously reported to be associated with high KLK4 levels in ovarian cancer generally." (PMID 23451143, 2013). "The association of KLK4 with aggressive cancer was identified in an RT-PCR study of KLK4 expression in 147 ovarian cancer tissue samples." (PMID 23319948, 2012). "Furthermore, overexpression of KLK4 induced proliferation and increased the risk for relapse and death in ovarian carcinoma patients." (PMID 30811511, 2019). "In line with our data, the stable combined KLK4–7 overexpression in ovarian cancer cell line reduced cell growth through a reduction in attachment to ECM and integrin downregulation." (PMID 35883559, 2022). "It has been reported that the concomitant expression of KLK4–7 in 3D ovarian cancer cells drives spheroid formation involving integrins." (PMID 35883559, 2022). "Keratin 19 (KRT19) is reported to be upregulated in response to the overexpression of the kallikrein related peptidase 4 (KLK4), with suggested a downstream increase of malignancy by lower sensitivity to paclitaxel treatment in ovarian cancer." (PMID 35406529, 2022). "Previous studies have shown that KLK4 can promote tumour proliferation, migration and invasion in ovarian cancer." (PMID 34476001, 2021). "Remarkably, we found that KLK4 is ectopically expressed in human colon cancer and ovarian cancer cells, which is one of the members of the cancer-related KLK family." (PMID 34012960, 2021). "KLK4 has been indicated to be a biomarker of prognosis in triple-negative breast cancer and ovarian cancer." (PMID 34561425, 2021). "Activation of the TGFβ pathway was also observed in a proteomic analysis of the secretome of an ovarian cancer cell line engineered to overexpress KLK4, KLK5, KLK6 and KLK7." (PMID 33255452, 2020). "Multivariable Cox regression analysis of KLK4 mRNA expression levels and patients survival in advanced high-grade ovarian cancer (FIGO III/IV)." (PMID 30811511, 2019). "In ovarian cancer, high levels of KLK4-7, 10 and 13 function as unfavorable indicators for prognosis, while elevated expression of KLK8, 9, 11, 14 and 15 are supposed to be favorable markers." (PMID 30811511, 2019).
ovarian cancer (continued). "Of note, however, Shih and co-workers observed only very low concentrations of KLK4 protein in effusion fluid of ovarian cancer patients." (PMID 30811511, 2019). "Univariate Cox regression analysis of KLK4 mRNA expression levels and patients’ survival in advanced high-grade ovarian cancer (FIGO III/IV)." (PMID 30811511, 2019). "Consistent with our findings, Obiezu and co-workers found that KLK4 mRNA is an independent unfavorable prognostic biomarker on OS in the subgroup of high grade ovarian cancer patients (n = 88) as well." (PMID 30811511, 2019). "Strikingly, upon addition of KLK4 mRNA into the multivariable model we showed that KLK4 remains an independent unfavorable predictive biomarker for OS in ovarian cancer." (PMID 30811511, 2019). "To validate the results obtained for KLK4, we used the Kaplan-Meier Plotter to perform an in silico analysis of publicly available Affymetrix-based mRNA data from ovarian cancer patients." (PMID 30811511, 2019). "Four KLKs (KLK4–6 and KLK15) are linked to the poor prognosis of ovarian cancer patients, while higher KLK9 and KLK14 levels are associated with a favorable course of the disease." (PMID 25436002, 2015). "It has become evident that expression of many KLKs is regulated by steroid hormones in a tissue-specific manner, such as KLK2, PSA/KLK3 and KLK4 by androgen in prostate and breast cancer cells, and KLK4 by estrogen in endometrial and ovarian cancer cells." (PMID 24043563, 2014). "To determine the association of high KLK4 levels with prognosis in EOC specifically, compared to that reported previously for ovarian cancer patients with mixed histotypes, we performed RT-qPCR in a cohort of cDNA samples from 38 serous EOC patients." (PMID 23451143, 2013). "A total of 11 KLKs (KLK4-11, 13–15) were reported to be dysregulated in ovarian cancer, mostly up-regulated." (PMID 20354523, 2010). "KLK4 has been identified as an indicator for breast, prostate, and ovarian cancer progression." (PMID 36814474, 2023). "Moreover, circ_0025033 was upregulated, and its knockdown inhibited ovarian cancer cell viability and metastasis through targeting the miR-330-5p/KLK4 axis." (PMID 36273140, 2022). "The results of these reports indicate that KLK4 may be a valuable biomarker in the diagnosis and treatment of ovarian cancer." (PMID 34476001, 2021). "In addition, Xi and co-workers found that KLK4 is related with paclitaxel resistance in ovarian cancer." (PMID 30811511, 2019). "Obiezu and co-workers found that KLK4 mRNA was more frequently expressed in advanced-stage and high-grade ovarian cancers, in comparison with patients with early stage and lower grade ovarian cancers, suggesting that elevated KLK4 expression is correlated with more aggressive tumor subtypes." (PMID 30811511, 2019). "In the context with previous findings indicating an important tumor biological role of KLK4 in regulation of cell proliferation, adhesion, migration, and invasion, KLK4 may represent an attractive novel target for tumor therapy in ovarian cancer." (PMID 30811511, 2019). "The results of these reports suggest that KLK4 may represent a valuable biomarker in diagnosis and treatment of ovarian cancer." (PMID 30811511, 2019). "Furthermore, these findings are in agreement with former studies showing that elevated KLK4 protein and mRNA levels are both correlated with more invasive and aggressive ovarian cancer phenotypes." (PMID 30811511, 2019). "The results of the present study, obtained in a well-defined, homogenous cohort of patients afflicted with advanced high-grade serous ovarian cancer, are in line with previous reports describing high KLK4 levels as an unfavorable marker in ovarian cancer patients." (PMID 30811511, 2019). "In OV-Mz-6 ovarian cancer cells, expression of KLK4–7 leads to elevated TGFβ-1 signaling." (PMID 29249975, 2017).
ovarian cancer (continued). "Analysis of kallikreins 4–8, 10, 11, 13, and 14 levels in effusion supernatants obtained from 221 ovarian cancer samples and nonneoplastic diseases demonstrated that, with the exception of KLK4, all kallikreins were expressed at higher than normal levels in ovarian cancer effusions." (PMID 23319948, 2012). "Intrinsic expression of the cell membrane-localized protein CD157 in ovarian cancer cells has been shown to promote transmesothelial migration, whereas similar prometastatic effects have been demonstrated with overexpression of the tumor-secreted peptidase kallikrein-related-peptidase 4 (KLK4)." (PMID 37545408, 2023). "Additionally, several members of the KLK family, including KLK4, can serve as signal molecules controlling cell functions through the protease-activated receptors (PARs), being of concern in the progression of several cancers including ovarian cancer." (PMID 30811511, 2019). "However, it has been reported that KLK4 can be activated by MMP20 during tooth development in the pig suggesting that MMP20 or an MMP with a similar specificity may activate KLK4 in the ovarian cancer microenvironment." (PMID 23451143, 2013). "Daniela Loessner and colleagues observed that kallikrein-related peptidase 4, 5, 6, and 7 (KLK4-7) overexpression in ovarian cancer cells spheroids with integrin activation produces PCa after nine weeks of the inoculation in the peritoneal cavity in mice." (PMID 33669017, 2021). "Elevated KLK4 and KLK7 expression levels are obviously involved in paclitaxel resistance in ovarian cancer." (PMID 30811511, 2019). "It has been reported that at the transcriptional level, KLK4–8, KLK10 and KLK14 are highly expressed in ovarian cancer tissues." (PMID 24043563, 2014). "High protein levels of KLK4–7 and KLK10 have been found in ovarian cancer tissues, while KLK5–8, KLK10, KLK11, KLK13 and KLK14 were found in ascites fluid from ovarian cancer patients as reviewed." (PMID 24043563, 2014). "We have reported that combined expression of KLK4, KLK5, KLK6, and KLK7 in OV-MZ-6 ovarian cancer cells regulates integrin expression, cell adhesion, and promotes a malignant phenotype." (PMID 27605189, 2013). "In ovarian cancer, KLK4-KLK8, KLK10 and KLK14 are upregulated and we previously reported that KLK4 and KLK7 were highly expressed in the most lethal histotype, serous EOCs." (PMID 23451143, 2013). "KLK4 has been shown to be expressed in ovarian cancer tissue and cell lines, but is absent in non-malignant ovarian tissues." (PMID 30811511, 2019). "KLK4, KLK5, KLK6 and KLK7 have been found related to the prognosis of ovarian cancer." (PMID 27825132, 2016). "Elevated expression of KLK4, KLK5, KLK6, and KLK7 are linked to multi-cellular aggregation of ovarian cancer cells and non-responsiveness of patients to paclitaxel." (PMID 27605189, 2013). "Similarly, KLK4 and KLK9 share prognostic value in ovarian cancer, with higher expression of KLK5 correlating with poor prognosis." (PMID 23319948, 2012). "Overexpression of several members of the kallikrein-related peptidase (KLK) family, including KLK4, has been reported in ovarian cancer tissue, consistent with the fact that elevated levels of KLK protein are often also found in serum and in effusion fluids of ovarian cancer patients." (PMID 30811511, 2019).
prostate carcinoma (31 papers, 2002 to 2025). A carcinoma that arises from epithelial cells of the prostate gland. "As KLK3/PSA and KLK4 promote the epithelial–mesenchymal transition (EMT) of prostate cancer cells and their dissemination, KLK4 is also strongly linked to aggressive PCa, whereas knockdown of the KLK4 gene significantly reduces PCa cell proliferation." (PMID 41516101, 2025). "Successful in planta production was also extended to an engineered SFTI-1 variant (SFTI-FCQR) that inhibits human kallikrein-related peptidase 4, a target for prostate cancer treatment." (PMID 29309615, 2018). "KLK4 overexpression has been reported to be associated with prostate cancer stage, although the direction of effect differed for KLK4 mRNA (associated with advanced stage) versus KLK4 protein (early stage tumours)." (PMID 22970239, 2012). "Our well-sized study indicates a possible contribution of SNPs in the KLK4 gene to decreased risk of prostate cancer." (PMID 22970239, 2012). "Part of our study design was to exclude KLK4 SNPs already assessed in GWAS, except for those reported to be associated with prostate cancer at the P<0.05 level in CGEMS." (PMID 22970239, 2012). "We performed a comprehensive investigation of the role of variation in the KLK4 gene in prostate cancer risk and/or tumour aggressiveness by assessing the majority of SNPs that have not been covered by previously performed GWA studies." (PMID 22970239, 2012). "Our findings provide suggestive evidence of a role for genetic variation in the KLK4 locus in prostate cancer predisposition." (PMID 22970239, 2012). "Five KLK4 SNPs – rs198969, rs198968, rs1654552, rs1654551 and rs1654553 - were assessed for association with prostate cancer risk in the Cancer Prostate in Sweden (CAPS) 1 sample set of over 1,400 cases and 700 controls and none were found to be associated." (PMID 22970239, 2012). "The only SNP located in the KLK4 coding region found to be marginally associated with prostate cancer risk was rs1654551." (PMID 22970239, 2012). "It is well known that genetic variation has the potential to affect gene expression and/or various protein characteristics and hence we sought to investigate the possible role of single nucleotide polymorphisms (SNPs) in the KLK4 gene in prostate cancer." (PMID 22970239, 2012). "Recently, KLK-4 has been implicated as a proliferative factor in prostate cancer cells and a potential mediator of the epithelial to mesenchymal transition." (PMID 22641253, 2012). "The effect of salinomycin on KLK4-PLZF interaction may provide additional insights into the multiple pathways that are targeted by this drug to cause prostate cancer inhibition." (PMID 27557496, 2016). "Our study of approximately 1,300 cases and 1,300 male controls provided suggestive evidence that several KLK4 SNPs may be associated with decreased risk of prostate cancer, and bioinformatic analysis provides evidence that some of these have potential biological relevance in prostate cancer." (PMID 22970239, 2012). "In prostate cancer, KLK2 and KLK4 have become valuable diagnostic tools and drug targets, as in the 4K test and with a promising new monoclonal Fab." (PMID 41516101, 2025). "Studies comparing KLK gene expression between prostate cancer and healthy controls have shown stronger statistical correlations between malignancy status and KLK4 compared with KLK351." (PMID 36906603, 2023). "Herein, we first demonstrated how miR-378 exerts anti-prostate cancer (PCa) actions by influencing multiple target genes, including KLK2, KLK4, KLK6, and KLK14, which are implicated in PCa development, cell proliferation, and cell survival." (PMID 35681793, 2022). "In patient cohorts we found significantly higher expression of both KLK4T2 and KLK4 in benign prostatic hyperplasia compared to both primary prostate cancer and bone metastasis." (PMID 34884832, 2021).